ENSG00000201541
Synonyms: LOC124900377
Gene: Small nucleolar RNA gene on chromosome 16 (24,333,415 to 24,333,547, reverse strand). Ensembl gene ENSG00000201541.
Gene Ontology:
Biological process: RNA processing
Cellular component: nucleolus
Homologues: Paralogues in human: SNORA1B (86% identical), SNORA1 (86% identical).